MIR98 (microRNA 98)
Synonyms: hsa-mir-98; MIRLET7L; MIRN98; miR-98
Gene: MicroRNA gene on chromosome X (53,556,223 to 53,556,341, reverse strand). Ensembl gene ENSG00000271886.
Gene Ontology:
Biological process: miRNA-mediated post-transcriptional gene silencing
Cellular component: RISC complex
Homologues: Orthologues: chimpanzee ptr-mir-98 (100% identical), rat Mir98 (81% identical), mouse Mir98 (79% identical), guinea pig MIR98 (74% identical), macaque mml-mir-98 (67% identical), dog MIR98 (66% identical), pig ssc-mir-98 (66% identical), tropical clawed frog xtr-mir-98 (65% identical), zebrafish dre-let-7h (62% identical). Paralogues in human: MIRLET7F1 (54% identical), MIRLET7A1 (46% identical), MIRLET7C (45% identical), MIRLET7A3 (45% identical), MIRLET7D (45% identical), MIRLET7F2 (45% identical), MIRLET7E (41% identical), MIRLET7G (41% identical), MIRLET7I (41% identical), MIRLET7A2 (40% identical).
Diseases named in the same sentence as MIR98 in open-access papers:
MIR98 is named in the same sentence as 1 disease in open-access papers, as found by Europe PMC text mining. Sharing a sentence is not in itself a finding about the gene and the disease. The quoted sentences say what the papers report.
tumor (2 papers, 2021 to 2022). "Furthermore, the sponging of the CYP19A1 mRNA by MIR98 contributed to estrogen depletion and decreased tumor cell proliferation, migration, invasion, and angiogenesis, suggesting application of MIR98 as a therapeutic and diagnostic molecule in clinical settings." (PMID 33920789, 2021). "CASKIN2, TLE2, USP20, SPRN, ARSG, MIR106B, and MIR98 were considered to be substantially expressed in the low-risk group, suggesting that these genes may be PAAD tumor suppressor genes." (PMID 35077391, 2022).